CCND1 (cyclin D1)
Diseases named in the same sentence as CCND1 in open-access papers (continued):
Sharing a sentence is not in itself a finding about the gene and the disease.
breast cancer (continued). "The a870g polymorphism of the CCND1 gene (rs603965) has been shown to be associated with breast cancer survival in a large Chinese population-based study and in a small population of patients with metastatic breast cancer." (PMID 18507837, 2008). "In breast cancer, amplification and over-expression of cyclin D1 has been associated with worse prognosis, but high expression of cyclin D1, in contrast, has also been associated with better prognosis." (PMID 18823530, 2008). "Multivariate analyses revealed several statistically significant SNP-SNP interactions associated with increased breast cancer risk including one between CCND1 Pro241Pro and COMT Met108/158Val polymorphisms." (PMID 18194538, 2008). "Analysis of the independent contribution of the CCND1 polymorphism to breast cancer risk has shown a statistically significant association with increased breast cancer risk in both Ontario and Finland." (PMID 18194538, 2008). "Our findings suggest that COMT and CCND1 alleles act in combination and contribute to breast cancer progression." (PMID 18194538, 2008). "Due to the complementary functional roles of COMT and CCND1, we have also investigated the combined effect of their genotypes in association with altered breast cancer risk." (PMID 18194538, 2008). "The magnitude of the increased combined risk effect was higher in Ontario compared to Finland; however a test for trend supported the association of increased breast cancer risk with increasing activity of both CCND1 and COMT genotypes in both populations." (PMID 18194538, 2008). "In the combined analysis, the higher activity alleles of the COMT and CCND1 is associated with increased breast cancer risk in both Ontario [OR: 2.22, 95%CI (1.49–3.28)] and Finland [OR: 1.73, 95%CI (1.08–2.78)] populations studied." (PMID 18194538, 2008). "Deregulated cyclin D1 expression is also linked to the development of resistance to hormone therapy in breast cancer." (PMID 17407548, 2007). "Overexpression of cyclin D1 has also been linked to the development of endocrine resistance in breast cancer cells." (PMID 17407548, 2007). "Among all Cyclins, Cyclin D1 expression is one of the hallmarks of breast cancer progression and is considered as a positive diagnostic marker." (PMID 17668048, 2007). "Treatment of LnCap prostate cancer cells and various breast cancer cell lines with 25 μM curcumin for 3 h resulted in a near-total loss of cyclin D1 expression." (PMID 17407548, 2007). "Two genes located within this amplicon, EMS1, encoding cortactin, and CCND1 encoding cyclin D1, were both considered to act as oncogenes in breast cancer, because increased expression of both cortactin and cyclin D1 correlated well with 11q13 amplification." (PMID 16536875, 2006). "One of the first transcription factors found to associate with cyclin D1 was estrogen receptor (ER) alpha, which serves a critical role in breast cancer development and management." (PMID 16863592, 2006). "We thus wished to investigate further, the mechanisms underlying the effect of TSA on cyclin D1 degradation in MCF-7 breast cancer cells." (PMID 16504004, 2006). "Cyclin D1 appears to be critical in some pathways of mammary tumorigenesis, because cyclin D1-deficient mice are resistant to breast cancers induced by the c-neu and Ha-ras oncogene, but remain fully sensitive to breast cancers induced by c-myc and Wnt-1." (PMID 16536875, 2006). "Since cyclin D1 is associated with a favourable prognosis in breast cancer and Rb and p16 are well-known tumour-suppressor genes, these results underline that ERK1 and ERK2 are not involved in proliferation in mammary carcinomas." (PMID 15928662, 2005). "The CCND1 gene, a key cell-cycle regulator, is often altered in breast cancer, but the mechanisms underlying CCND1 dysregulation and the clinical significance of CCND1 status are unclear." (PMID 11870541, 2002).
breast cancer (continued). "Greater CCND1 copy numbers are associated with greater histopathological grade and high proliferation, indicating that CCND1 may be involved in the formation of breast cancer." (PMID 40384436, 2025). "Cyclin D1 is an oncogene that is frequently amplified in human breast cancer, regulates cell-cycle progression, and is associated with chemoresistance and decreased overall survival in patients with ER+ breast cancers." (PMID 39804138, 2025). "Similarly, a mutation in the breast-cancer risk SNP rs75915156 leads to the upregulation of the oncogene CCND1 in breast cancer cells." (PMID 40631184, 2025). "However, in breast cancers, it is overexpressed in around 50% of all cancers, with overexpression of CCND1 associated with poor outcomes." (PMID 39940977, 2025). "Similarly, a mutation in the breast cancer risk SNP rs75915156 upregulates the oncogene CCND1 in breast cancer cells." (PMID 40998810, 2025). "Further studies are needed to clarify the roles of CCND1 polymorphism, rs9344, in breast cancer." (PMID 40321701, 2025). "For instance, Cyclin D1 is a crucial regulator of the G1-S transition checkpoint of the cell cycle, and its abnormal upregulation is implicated in carcinogenesis and progression of human breast carcinoma." (PMID 40952540, 2025). "Usually, breast cancer development is associated with the amplification of cyclin D1 and its high expression, respectively, the high expression of cyclin E in 60% of breast tumors and a mitogenic effect of cyclin D1 exerted by an estrogen-dependent mechanism." (PMID 39598664, 2024). "CCND1-encoded cyclin D1 was known to be upregulated in breast cancer tissues." (PMID 37310654, 2023). "The expression of biomarkers, too, was consistent with human breast cancers resulting in a poor prognosis, with a gradual loss in ER, progesterone receptor, as well as integrin-β1 along with the persistent expression of cyclin-D1 and ErbB2/Neu (equivalent to human HER2)." (PMID 37297024, 2023). "The CCND1 gene encodes cyclin D1 is frequently amplified in human breast cancers." (PMID 36358806, 2022). "CCND1 is associated with cell cycle dysregulation in breast cancer." (PMID 34983363, 2022). "Its over-expression triggered proliferation and anchorage-independent growth in cells and acted as an oncomiR in breast cancer initiation through associating with cyclin D1 and c-Myc and downregulating SOX7, a tumor suppressor and a downstream target of miR-492." (PMID 36539576, 2022). "Interestingly, a minority of reports suggest that a high level of cyclin D1 expression is associated with a favorable prognosis in breast cancer and clear renal cell carcinoma." (PMID 36059670, 2022). "Similarly, a study analyzed the immunohistochemical (IHC) positivity of cyclin D1 in invasive ductal and moderately differentiated breast cancer cases, which was associated with significantly poorer prognoses in these patients." (PMID 33920506, 2021). "The goal of the current study is to examine the expression levels of miRNA-373 and VEGF, and cyclin D1 in Egyptian breast cancer patients as minimal noninvasive molecular markers for diagnostic purposes, and their impact on clinical characteristics of breast cancer." (PMID 34089425, 2021). "In addition, CCND1 is also a well-known oncogene that plays a key role in cell cycle progression and whose overexpression in breast cancer has been linked to poor prognosis." (PMID 35011637, 2021). "Cyclin D1 is a critical cell cycle regulator and a candidate proto-oncogene, whose deregulation has been implicated in the pathogenesis of several cancer types, including breast cancer." (PMID 34539418, 2021).
breast cancer (continued). "However, a strong difference in curve is noted between low and high expression level, which shows that the high expression of CCND1 is found to be associated with high number of patients at risk which gives a less survival rate for patients with breast cancer." (PMID 33438725, 2021). "While up-regulation of CCND1 is commonly associated with increased migratory capacity, chemotherapy resistance and poor outcomes in various cancers, the down-regulation of CCND1 in breast cancer has been linked to excessively infiltrative growth and poor prognosis." (PMID 33923996, 2021). "Several studies observed that CCND1 rs9344 is associated with breast cancer risk, but the relationship with breast cancer characteristics is still unknown." (PMID 34441352, 2021). "These tumors express Cyclin D1, a tumor-associated antigen common in breast cancers." (PMID 35095862, 2021). "Furthermore, the Kaplan–Meier plotter has explained that high expression of CCND1 is associated with less survival rate of breast cancer patients." (PMID 33438725, 2021). "Additionally, research data based on in vitro and clinical studies implicated an increased cyclin D1 gene expression and amplification in ~45–50% of breast cancer cases." (PMID 33920506, 2021). "Indeed, ATR-deficient cells enhanced the growth of breast cancer cells, which was confirmed by showing the expression of high levels of Ki-67 and cyclin D1." (PMID 32414408, 2020). "A very recent database investigation suggests that CCND1 amplification may be associated with poor clinical response to antiestrogen therapy in breast cancer patients, through suppressing the antitumor immunity in TME." (PMID 33317149, 2020). "Besides, the previous study indicated that CCND1 overexpression was associated with a more favorable prognosis and responded better to anti-estrogen therapy in breast cancer." (PMID 33363566, 2020). "In a previous study carried out in MCF-7 cell-based breast cancer xenograft model in nude mice, methylselenocysteine led to synergistic inhibition of tumor growth that was associated with inhibition of cyclin D1 as well as inhibition of cell proliferation and induction of apoptosis." (PMID 32213883, 2020). "Furthermore, the cell cycle effect of miR-17/20 disappears after Cyclin D1 silencing and in Cyclin D1-deficient breast cancer cells." (PMID 33317149, 2020). "Cyclin D1 expression is associated with poor prognosis of ER+ breast cancers." (PMID 32210163, 2020). "In addition, in breast cancer cells of the HER2+ subtype OOS caused the increase in the amount of p27 that was accompanied by a decrease in cyclin D1 and Rb phosphorylation." (PMID 32878230, 2020). "To gain molecular insights into the biologic effects exerted by OHPg/PR-B on the migratory and invasive phenotype of breast cancer cells, we focused our interest onto Cyclin D1 (CD1), recently increasingly associated with metastasis in clinical studies and in vivo experiments." (PMID 31426542, 2019). "Amplification and overexpression of cyclin D1 may contribute to its oncogenicity, and the oncogenic predisposition occurs within luminal tumors, more specifically within Luminal B breast cancers 32-34." (PMID 31632494, 2019). "Furthermore, cyclin D1 associates with p21 in metastatic breast cancer cells, and is a well-characterized oncogene that is frequently overexpressed in human lung carcinomas." (PMID 29416684, 2018). "PAL, a specific CDK 4/6 inhibitor, could cause cell cycle arrest in breast cancer cell lines with functional Rb and high CCND1 expression but low CDKN2A expression." (PMID 30236142, 2018).
breast cancer (continued). "On subgroup analysis stratified according to cancer types showed significant association of CCND1 polymorphism and increased breast cancer risk in dominant model (GG vs GA+AA: OR = 2.75, 95%CI = 1.54–4.90, P=0.0006), allelic model (G vs A: OR = 1.63, 95%CI = 1.22–2.19, P=0.001)." (PMID 30361291, 2018). "An important functional single nucleotide polymorphism (SNP) in CCND1 gene (rs9344) G870A, may influence the breast cancer development." (PMID 30361291, 2018). "Subgroup analysis according to cancer types presented significant association of CCND1 polymorphism and increased breast cancer risk in dominant model (GG vs GA+AA: OR = 2.75, 95%CI = 1.54–4.90, P=0.0006) and allelic model (G vs A: OR = 1.63, 95%CI = 1.22–2.19, P=0.001)." (PMID 30361291, 2018). "Ours is the first report suggesting an association between ID4 and CCND1 in breast cancer." (PMID 30139383, 2018). "Similarly, TBLR1 was implicated in the development and progression of breast cancer via the activation of the β-catenin signaling pathway and cyclin D1-transactivation." (PMID 28977891, 2017). "The under-expression of miR-497, 376c and 1271 in Lebanese breast cancer tissues could explain the observed upregulation of CCND1 that encodes for cyclin D1, promotor of cell cycle progression through inhibition of tumor suppressor Rb." (PMID 29203780, 2017). "In view of the finding that the cyclin D1 gene encodes the regulatory subunit of the holoenzyme that phosphorylates pRB, and RB phosphorylation is increased in human breast cancer-associated fibroblasts, we determined the abundance of cyclin D1 in the stroma of human breast cancers." (PMID 29137220, 2017). "Additionally, since amplification of the cyclin D gene CCND1 is one of the reasons for high cyclin D1 expression in breast cancer, we also studied the copy number of CCND1, and its association to cyclin D1 expression and prognosis." (PMID 28528450, 2017). "However, the underlying mechanisms of CCND1 overexpression and its connection to breast cancer progression are poorly understood." (PMID 26799586, 2016). "Moreover, β-catenin transactivation has been associated with cyclin D1 overexpression in breast cancer." (PMID 28036353, 2016). "However, a correlation was shown for ER-positive breast cancers, demonstrating that cyclin D1 was strongly linked with estrogen and poor prognosis in ER-positive cases." (PMID 26404249, 2015). "In addition, several studies demonstrated that CCND1 amplifications were linked to resistance mechanisms, such as endocrine resistance in breast cancers, or BRAF inhibitor resistance in BRAF V600E mutated melanomas." (PMID 25596748, 2015). "Moreover, it is known that cyclin D1 is linked with estrogen signaling and can act as a cellular ER sensor and contribute to ER activation in breast cancer cells." (PMID 26404249, 2015). "beta-catenin transactivation has been associated with cyclin D1 overexpression in breast cancer." (PMID 24931005, 2014). "The expression of ERα usually increases both levels of Bmi1 and cyclin D1, while loss of ERα-coupled Bmi1 activity may result in aberrant p16INK4a expression and is also generally consistent with a more aggressive breast cancer phenotype." (PMID 24559156, 2014). "Interestingly, in a cohort of male breast cancer patients cyclin D1 overexpression was predicative of better patient survival, while high levels of cyclin A and B expression increase the risk for breast cancer related death by 2–3 fold." (PMID 23755153, 2014). "However, underlying mechanisms of CCND1 overexpression and its connection to breast cancer progression are poorly understood." (PMID 25520916, 2014).
breast cancer (continued). "Several studies have found that amplification of CCND1 and the aberrant expression of protein are associated with cell proliferation and poor prognosis in some cancers, such as head and neck cancer, lung cancer, and breast cancer." (PMID 25204741, 2014). "It has previously been observed that reduced DACH1 expression occurs in invasive cancer compared to normal breast epithelium confirmed by our findings where DACH1 expression showed an inverse association with mitosis and cyclin D1 expression in breast cancer patient samples." (PMID 24392136, 2014). "In addition, overexpression of cyclin D1 is strongly associated with tamoxifen resistance in breast cancer cells." (PMID 24915301, 2014). "Cyclin D1 was associated with a good breast cancer prognosis but functioned independently of CDK4." (PMID 23336272, 2013). "Although cyclin D1 depletion by CG0009 may occur partly as a result of the decrease in ERα protein in MCF7 cells, we propose that this cyclin D1 decrease is a major cause of CG009-induced breast cancer cell death." (PMID 23565238, 2013). "The aim of our study was to characterise the association between CCND1 amplification and cyclin D1 protein expression and breast cancer recurrence in a large randomised cohort of postmenopausal patients with ER-positive breast cancer treated with endocrine therapy." (PMID 22475046, 2012). "The adenine-to-guanine (A/G) substitution at nucleotide 870 (CCND1 G870A polymorphism, rs603965) and excessive cyclin D1 activity are common in numerous human tumors, including breast cancer, lung cancer, head and neck cancers, gastric cancer, gynecological cancers, blood-related cancers, and CRC." (PMID 22606291, 2012). "ERα and cyclin D1 also activate the same set of genes linked to breast cancer progression." (PMID 24575359, 2012). "Loss of PHD1 may thus be anticipated to downregulate cyclin D1 levels and suppress mammary tumour proliferation." (PMID 21291529, 2011). "However, further studies have revealed that cyclin D1 can be associated with improved outcome in breast cancer, possibly due to the blocking effects of p27, which is often increased in parallel with cyclin D1." (PMID 20682066, 2010). "Gene amplification (11q13) as a mechanism for aberrant overexpression of cyclin D1 is associated with non- small cell lung cancers, head and neck squamous cell carcinomas, pancreatic carcinomas, bladder cancer, pituitary adenomas and breast carcinoma." (PMID 21176227, 2010). "The murine mammary tumor induced by PyMT shares many features with poor-prognosis human breast cancer such as a high frequency of distant metastases, persistent expression of biomarkers, ErbB2/Neu and cyclin D1, and loss of estrogen and progesterone receptor expression." (PMID 20846433, 2010). "Thus, our study is the first to show the statistically significant association of the CCND1 polymorphism with breast cancer in two independent, relatively large case control studies." (PMID 18194538, 2008). "It is apparent that future studies are necessary to determine the intricate mechanisms underlying tamoxifen resistance, and to elucidate the cause of events rendering CCND1 amplified premenopausal breast cancers not only resistant but possibly stimulated by this selective ER modulator." (PMID 18823530, 2008). "Genetically, our findings suggests that the individuals inheriting the combinations of high activity COMT and CCND1 alleles have relatively higher breast cancer risk probably due to simultaneous reduction in estrogen metabolism, and increase in cell proliferation." (PMID 18194538, 2008).